ADAM9 (ADAM metallopeptidase domain 9)
Diseases named in the same sentence as ADAM9 in open-access papers (continued):
Sharing a sentence is not in itself a finding about the gene and the disease.
viral infection (6 papers, 2015 to 2025). "Among the genes whose KO potentially promotes cell survival following virus infection, we found ADAM9, which has previously been implicated in EMCV entry into the cell." (PMID 41335465, 2025). "ADAM9 is implicated in a range of human diseases, including inflammatory diseases; however, its role in viral infection is unknown." (PMID 38755212, 2024). "Furthermore, we surmised that the deficient innate immune response to viral infection in Adam9 KO mice resulted in an increased viral load and accelerated mortality seen in these animals." (PMID 38755212, 2024). "Our results establish a mechanism of ADAM9-dependent protection of the heart during viral infection, unveiling a previously undiscovered role for ADAM9 in the type I IFN response to cytosolic viral RNA." (PMID 38755212, 2024). "Upon virus infection, the ADAM9-WT-transfected cells showed significant enhancement of co-localization between ACE2 and Rab5 compared to mock-transfected cells, proving that ACE2 was indeed endocytosed after virus infection." (PMID 37713503, 2023). "Our study reveals an insight into the mechanism of SARS-CoV-2 virus entry and elucidates the role of ADAM9 in virus infection." (PMID 37713503, 2023). "Together, these data indicate that EMCV can use both human and mouse ADAM9 to infect cells and that its metalloprotease activity is dispensable for virus infection." (PMID 31409686, 2019). "Taken together, Adam9 KO mice had increased viral replication in the heart resulting in acute myocardial damage, suggesting that ADAM9 may play a protective role during viral infection of the heart." (PMID 38755212, 2024). "Since we have demonstrated that ADAM9 functions at the early stages of virus infection, we next investigated whether the protease activity of ADAM9 participates in SARS-CoV-2 Spike Vpp binding or endocytosis." (PMID 37713503, 2023). "Our observation that soluble ADAM9 reduced virus infection hints toward a direct interaction." (PMID 31409686, 2019). "Additionally, ADAM9 can interact with ACE2, and co-expression of both proteins markedly enhances virus infection." (PMID 37713503, 2023). "Pharmacological inhibition of the metalloproteinase activity of ADAM9 did not affect virus infection." (PMID 31409686, 2019).
COVID-19 (5 papers, 2023 to 2026). A disease caused by infection with severe acute respiratory syndrome coronavirus 2. "Dysregulated ADAM9 activity has been implicated in several diseases, such as solid tumors, autoimmunity, inflammatory diseases, and coronavirus disease 2019." (PMID 41740737, 2026). "For instance, an increased expression of ADAM9 and others member of the metalloprotease protein family in the blood has been associated with tissue damage and identified as a potential drug target for COVID-19." (PMID 37047222, 2023). "It is, thus, tempting to speculate that the upregulation of ADAM9 in cancer patients may aggravate SARS-CoV-2 infection-causing COVID-19 severity, which still requires further evidence." (PMID 37713503, 2023). "This analysis found that increased ADAM9 RNA expression levels were detected in the serum of critically ill COVID-19 patients, further emphasizing the role that ADAM9 plays in SARS-CoV-2 infection." (PMID 39205219, 2024). "A higher ADAM9 RNA expression level was detected in the serum of critically ill COVID-19 patients." (PMID 37713503, 2023). "Of note, ADAM9 was identified as a key driver of SARS-CoV-2 severity in a multi-omics analysis of a young, comorbidity-free COVID-19 patient cohort." (PMID 39205219, 2024). "Recently, ADAM9 was identified as a key driver of SARS-CoV-2 severity using the multi-omics analysis of a young, comorbidity-free COVID-19 patient cohort to identify host genes that drive disease severity." (PMID 37713503, 2023). "The researchers used Integrative AI, ML, and probabilistic programming to distinguish non-critical and critical patients with COVID-19 and identified ADAM9 as a driver of disease severity and a candidate therapeutic target." (PMID 38666857, 2024).
esophageal squamous cell carcinoma (5 papers, 2016 to 2023). Esophageal squamous cell carcinoma (ESCC) is a type of esophageal carcinoma (EC) that can affect any part of the esophagus, but is usually located in the upper or middle third. "Two published works have linked ADAM9 to Akt activity in esophageal squamous cell carcinoma and triple-negative breast cancer, respectively." (PMID 35780836, 2022). "It is worth noting that after high-level expression of miR-126, it can inhibit DNMT1, thereby affecting the expression level of ADAM9 through the pathway, and then regulating the related physiological functions of esophageal squamous cell carcinoma." (PMID 32875951, 2020). "Therefore, the effects of ADAM9 KD on EGFR activation observed previously are likely specific to the esophageal squamous cell carcinoma cells examined, and there are alternative mechanisms through which ADAM9 regulates Akt in other cells and tissues." (PMID 35780836, 2022).
glioblastoma (5 papers, 2016 to 2023). The most malignant astrocytic tumor (WHO grade IV). "In these samples, we found that ADAM9 was upregulated in glioblastoma." (PMID 33260155, 2020). "There was a previous study which suggested that ADAM9 expression may contribute to glioblastoma invasion in U87 cells." (PMID 27571068, 2016). "While the exact composition of the secretome is largely unknown, related research has identified of insulin-like and opioid growth factors or proteins such as ADAM9, cathepsin B and neuropilin-1 as key components of the secretome of head and neck tumor or glioblastoma cells." (PMID 38092866, 2023). "The ADAM9 expression between lower-grade glioma (LGG) and glioblastoma (GBM) patients was compared and its association with progression-free survival (PFS) and overall survival (OS) was assessed to evaluate its prognostic value." (PMID 27571068, 2016).
Alzheimer disease (4 papers, 2016 to 2020). A progressive, neurodegenerative disease characterized by loss of function and death of nerve cells in several areas of the brain leading to loss of cognitive function such as memory and language. "While ADAM9 is broadly expressed, increased expression is associated with a wide variety of human cancers, as well as in Alzheimer's disease." (PMID 30914507, 2019). "However, promoter polymorphisms of ADAM9 have been reported to have a significant association with Alzheimer’s disease." (PMID 33096780, 2020). "On the contrary, in SY5Y neuroblastoma cells overexpressing APP, mimicking Alzheimer’s disease, treatment with ADAM9 pro-domains inhibited the activity of ADAM9 but reduced the production of Aβ peptides." (PMID 33096780, 2020). "An in-depth investigation of ADAM9 protein or mRNA levels in human subjects with APP-related disorders, such as Alzheimer’s disease and autism spectrum disorder, has yet to be performed." (PMID 32612155, 2020). "Further investigation of ADAM9, AGAP2 and PSEN1 levels in human subjects with APP-related disorders could help in understanding Alzheimer’s disease and autism spectrum disorders." (PMID 32612155, 2020). "In these studies, ADAM-9 prodomain was highly specific and the inhibition of ADAM-9, by its recombinant prodomain, regulated ADAM-10 activity controlling the release of soluble α-secretase enzyme, which is an important task in the therapy Alzheimer's disease." (PMID 27294958, 2016). "ADAM9 has been demonstrated to be involved in neurodegenerative disease by regulating the cleavage of amyloid precursor protein (APP), which might be relevant in Alzheimer’s disease." (PMID 33096780, 2020).
bladder cancer (4 papers, 2016 to 2022). "This suggested an association of knockdown of ADAM9 with inhibition of bladder cancer growth." (PMID 35740916, 2022). "At 18 h there was a significant difference in wound area between control cells (54.3 ± 4.11%) and ADAM9 knockdown cells (82.9 ± 16.6%), suggesting that ADAM9 may be associated with bladder-cancer cell migration." (PMID 35740916, 2022). "Many studies have reported an association between ADAM9 and cancer, including bladder cancer." (PMID 35740916, 2022). "Based on the results of TCGA analysis, the higher the stage of the bladder cancer, and the more malignant it is, the more ADAM9 mRNA is expressed." (PMID 35740916, 2022). "ADAM9 mRNA expression in high-grade bladder cancer was significantly higher than in low grade (p = 0.031)." (PMID 35740916, 2022). "We found that ADAM9 knockdown suppressed cell proliferation and migration in bladder cancer and that high-grade bladder cancer is correlated with higher expression of ADAM9." (PMID 35740916, 2022). "Since T24 is muscle-invasive bladder cancer, the results suggested that invasive bladder cancer cells are more dependent on ADAM9 signaling for progression." (PMID 35740916, 2022). "The average level of ADAM9 mRNA in stage IV bladder cancer patients was significantly higher than patients in stages I, II, and III (3094.24 vs. 2083.05, 2302, 2403.38, respectively) (p = 0.014)." (PMID 35740916, 2022). "Results suggested a possible correlation between exacerbation of bladder cancer and the expression of ADAM9." (PMID 35740916, 2022). "The specific regulatory mechanism is that miR-126 directly acts on ADAM9 through negatively regulated expression, and further regulates the invasion of bladder cancer cells by affecting its expression level." (PMID 32875951, 2020). "Some researchers have found that in bladder cancer tumor tissues and normal tissues adjacent to the cancer, the expression of ADAM9 is increased, and the degree of tumor deterioration is proportional to its expression level." (PMID 32875951, 2020). "This suggested that the inhibitory effect of ADAM9 knockdown on bladder cancer cell proliferation may be relatively high, compared with other cancer types." (PMID 35740916, 2022). "Our findings suggest that ADAM9 may be a new therapeutic target as well as a marker of poor prognosis in bladder cancer." (PMID 35740916, 2022). "ADAM9 expression was highly and significantly expressed in bladder cancer with surrounding carcinoma or invasive carcinoma (p < 0.001), suggesting that ADAM9 may be associated with the promotion of cell migration." (PMID 35740916, 2022). "Moreover, in the gene expression omnibus (GEO) study, bladder cancer with surrounding carcinoma and invasive carcinoma showed significantly high ADAM9 mRNA expression." (PMID 35740916, 2022). "The purpose of this study was to investigate the involvement of ADAM9 in the exacerbation of bladder cancer and to clarify whether ADAM9 can be a new therapeutic target for preventing bladder cancer cell EMT." (PMID 35740916, 2022). "That is, the expression level of ADAM9 can be used as a sign of poor prognosis in bladder cancer." (PMID 32875951, 2020). "In addition, miR-126 has been shown to directly target ADAM9 thereby decreasing the invasiveness of bladder cancer cells." (PMID 27827458, 2016). "Therefore, ADAM9 may be a useful prognostic marker, especially in that it correlates with bladder cancer stage classification and grade." (PMID 35740916, 2022). "In bladder cancer, the expression levels of miRNA-126 and ADAM9 showed a significant negative correlation." (PMID 32875951, 2020).
brain tumor (4 papers, 2005 to 2022). "It has also been reported that TNC is a promoter of the invasiveness of brain tumor-initiating cells through a mechanism involving ADAM-9 proteolysis via the c-Jun NH2-terminal kinase pathway." (PMID 35968275, 2022). "Finally, the expression levels of USP39/ADAM9 in the brain tumor were detected by western blotting and IHC analysis." (PMID 33811456, 2022). "Another recent study identified that ADAM9, through potentially regulating the activity of tenascin-C protein, might stimulate the invasiveness of brain tumor-initiating cells." (PMID 27571068, 2016). "In addition, we detected the expression levels of USP39, ADAM9 and integrin β1 in the brain tumor." (PMID 33811456, 2022).
breast tumor (4 papers, 2010 to 2018). "More recently, the recombinant disintegrin domain of ADAM9 was demonstrated to strongly inhibit MDA-MB-231 breast tumor cell invasion on matrigel in vitro, thus suggesting a key role for this domain in the process of tumor cell invasion." (PMID 22069567, 2010). "Moreover, ADAM9 silencing completely inhibited breast tumor cell in vitro invasion on matrigel." (PMID 22069567, 2010).
cervical cancer (4 papers, 2014 to 2023). A primary or metastatic malignant neoplasm involving the cervix. "The objective of this study was to investigate ADAM9 expression in cervical cancer and to determine the factors associated with ADAM9-positive expression." (PMID 31030477, 2019). "Therefore, the objective of the present study was to investigate the proportion of ADAM9 expression in three common types of cervical cancer and to study the factors associated with ADAM9-positive expression." (PMID 31030477, 2019). "For with every 1-mm increment in tumour size, cervical cancer patients had a 1.08 odds chance of having ADAM9-positive expression (95% CI 1.02, 1.13; p = 0.004)." (PMID 31030477, 2019). "Of the 95 cervical cancer patients included in the study, 72 (75.8%) patients showed positive ADAM9 expression." (PMID 31030477, 2019). "Cervical cancer cells’ culture is inhibited after treated with miR-126, a micro-RNA that specified to target ADAM9 gene." (PMID 31030477, 2019). "The authors suppose that the prevalence of ADAM9 expression is high in aggressive tumor types and, taking into account the detected ADAM9 expression in various cervical cancer histotypes, they recommend further studies of the relationship between ADAM9 expression and tumor development." (PMID 34830452, 2021). "Given the expression of ADAM9 in various types of cervical carcinomas, the findings presented herein could serve as a stepping stone for further studies on the relationship between ADAM9 expression and tumorigenesis." (PMID 31030477, 2019). "Thus, it was established that the expression of ADAM9 is low in the squamous epithelium of the cervix and increases in the foci of CIN3 and the tissue of squamous cervical cancer; to identify the diagnostic and prognostic value of ADAM9 in cervical cancer, further studies are recommended." (PMID 34830452, 2021). "Cervical cancer patients who had distant metastasis had 12.82 times chance of having ADAM9-positive expression as compared with cervical cancer patients without distant metastasis (95% CI 1.91, 86.13; p = 0.009)." (PMID 31030477, 2019). "Of 47 patients with cervical cancer, 8, 17, 13, and 9 cases showed no expression, 1+, 2+, and 3+ of RCAS1, respectively, while 7, 8, 11, and 21 cases had no expression, 1+, 2+, and 3+, respectively, for ADAM9." (PMID 25177692, 2014).
colorectal cancer (4 papers, 2021 to 2024). A primary or metastatic malignant neoplasm that affects the colon or rectum. "We found that ADAM9 expression is elevated in human colorectal cancer (CRC) tissues and that knockdown (KD) of ADAM9 inhibits the migration and invasion of SW620 and HCT116 CRC cells by reducing the activity of Akt kinase, which is antagonized by ephrin-Bs." (PMID 35780836, 2022). "Nevertheless, these data still provide further evidence that ADAM9 may influence MTORC1 signaling in MM, as has been described for colorectal cancer cells." (PMID 39261477, 2024).
esophageal cancer (4 papers, 2021 to 2025). A primary or metastatic malignant neoplasm involving the esophagus. "We provide initial proof for this notion by showing that ADAM9 is upregulated in, amongst others, bladder, colon, duodenum, and esophageal cancers." (PMID 34282781, 2021). "More importantly, CM derived from bladder, duodenum, colorectal, and esophageal cancer cell lines efficiently cleaved the ADAM9-substrate—indeed indicating that our ADAM9-MSN platform might be applicable to multiple types of cancer." (PMID 34282781, 2021). "Furthermore, ADAM9 is a transcription factor that encourages angiogenesis in esophageal cancer." (PMID 39898241, 2025). "In patients with early-stage (stage I and II) esophageal cancer who received curative esophagectomy, those with positive ADAM9 staining had a shorter survival time than those with negative ADAM9 staining (P < 0.01)." (PMID 36572816, 2023).
triple-negative breast carcinoma (4 papers, 2021 to 2023). An invasive breast carcinoma which is negative for expression of estrogen receptor (ER), progesterone receptor (PR), and human epidermal growth factor receptor 2 (HER2). "In triple-negative breast cancer (TNBC), higher ADAM9 expression correlates significantly with poorer outcomes, while inhibition of ADAM9 expression lowers TNBC cell aggressiveness by suppressing AKT/NF-κB signaling." (PMID 36778124, 2023).
astrocytic tumor (3 papers, 2005 to 2021). A glial tumor of the brain or spinal cord showing astrocytic differentiation. "Further analysis of the association between ADAM9 expression and different histological types of LGG revealed that astrocytic tumors had significantly higher expression than oligodendroglial tumors (6.051 ± 0.460 vs. 4.228 ± 0.231, p < 0.001, t-test)." (PMID 27571068, 2016). "In addition, among the LGG patients, aggressive astrocytic tumors displayed significantly higher ADAM9 expression than oligodendroglial tumors (p < 0.001, t-test)." (PMID 27571068, 2016). "Also, a significant difference in the ADAM9 mRNA expression was observed between LGG patients with different histological characteristics, and astrocytic tumors, which are more aggressive, had significantly higher ADAM9 mRNA expression than oligodendroglial tumors." (PMID 27571068, 2016). "The study demonstrated that GBM patients had significantly higher expression of ADAM9 in comparison to LGG patients, while among LGG patients, aggressive astrocytic tumors displayed significantly higher ADAM9 expression than oligodendroglial tumors." (PMID 34638718, 2021).
chronic obstructive pulmonary disease (3 papers, 2020 to 2025). A chronic and progressive lung disorder characterized by the loss of elasticity of the bronchial tree and the air sacs, destruction of the air sacs wall, thickening of the bronchial wall, and mucous accumulation in the bronchial tree. "Smoking is a significant environmental factor linked to KRAS mutations in LUAD patients and increased ADAM9 expression in individuals with chronic obstructive pulmonary disease." (PMID 40429751, 2025). "ADAM9 also stimulates the inflammatory process through polymorphonuclear leukocytes, macrophages, and epithelial cells in some inflammatory diseases, such as acute lung injury or chronic obstructive pulmonary disease (COPD)." (PMID 33096780, 2020).
Diabetes (3 papers, 2016 to 2025). "This study investigated the roles of mir-20a-5p and its predicted target circ-ADAM9 in EPCs treated with high glucose (30 mM) and in a diabetic mouse hind limb ischemia model." (PMID 32661238, 2020). "To determine the effect of diabetes on ADAM-9, we analyzed ADAM9 mRNA and protein expression in macrophages after HG treatment for 48 hours." (PMID 27827458, 2016). "In the present study, we demonstrate that diabetes-mediated decrease in miR-126 leads to a corresponding increase in its target, ADAM9, which in turn cleaves MERTK (inactivates downstream engulfment signaling), thus resulting in defective macrophage efferocytosis of apoptotic cardiomyocyte." (PMID 27827458, 2016). "In summary, we describe a novel cellular pathway involved in diabetic efferocytosis, wherein diabetes-induced decrease in miR-126 expression results in upregulation of ADAM9 expression that in-turn leads proteolytic cleavage of MerTK and formation of inactive sMer." (PMID 27827458, 2016).